PDZD8 (PDZ domain containing 8)
Description:
Lipid transfer and molecular tethering protein, which plays a key role in the formation of membrane contact sites between the endoplasmic reticulum and other organelles, such as late endosomes/lysosomes and mitochondria. Faciliates the exchange of lipids at membrane contact sites between the endoplasmic reticulum and organelles by mediating the transport of lipids, such as ceramide, cholesterol and phosphatidylserine. Also acts as a molecular glue by undergoing liquid-liquid phase separation, forming condensates that mediate stable adhesion between endoplasmic reticulum and surrounding organelles, connecting two distinct membrane-bound vesicles coupled together. Connects the endoplasmic reticulum to late endosomes/lysosomes, facilitating the exchange of lipids, which is crucial for membrane remodeling and processes, such as neurite outgrowth. PDZD8-dependent endoplasmic reticulum-mitochondria membrane tethering is essential for endoplasmic reticulum-mitochondria Ca(2+) transfer. In neurons, involved in the regulation of dendritic Ca(2+) dynamics by regulating mitochondrial Ca(2+) uptake in neurons. Mediates lysosomal vacuolation, a process during which lysosomes abnormally enlarge into large membrane-bound sacs in response to stress such as osmotic stress: acts by mediating bulk lipid transfer from the endoplasmic reticulum to lysosomes, leading to vacuole formation. Plays an indirect role in the regulation of cell morphology and cytoskeletal organization. May indirectly inhibit herpes simplex virus 1 infection at an early stage.
Synonyms: LYVAC; PDZK8; bA129M16.2; FLJ34427; IDDADF
Tractability: Small molecule: a structure with a bound ligand is known. Antibody: UniProt predicts a signal peptide or a membrane-spanning region; the Human Protein Atlas places it where antibodies can reach. PROTAC: ubiquitination databases record sites on it; its protein half-life has been measured.
Gene: Protein-coding gene on chromosome 10 (117,277,274 to 117,376,020, reverse strand). Ensembl gene ENSG00000165650.
Subcellular location: Endoplasmic reticulum membrane
Subcellular location (Human Protein Atlas): Nucleoli fibrillar center; Plasma membrane
Gene Ontology:
Molecular function: endoplasmic reticulum-endosome tether activity; endoplasmic reticulum-organelle membrane tether activity; lipid transfer activity; mitochondrion-endoplasmic reticulum membrane tether activity; molecular condensate scaffold activity; protein binding; lipid binding
Biological process: lysosome organization; mitochondrial calcium ion homeostasis; neuron projection development; organelle localization by membrane tethering; response to osmotic stress; intermembrane lipid transfer; lipophagy
Cellular component: endoplasmic reticulum membrane; endoplasmic reticulum-endosome membrane contact site; membrane; mitochondria-associated endoplasmic reticulum membrane contact site; mitochondrion
Genetic constraint (gnomAD): Loss-of-function variants: 13 observed, 82.5 expected, observed/expected ratio (o/e) 0.16, 90% interval 0.1 to 0.25. The upper end of that interval is the gene's LOEUF score, 0.25, which puts it in group 1 of 6, group 1 being the genes least tolerant of losing a copy. Missense variants: 1,178 observed, 1,442.7 expected, observed/expected ratio (o/e) 0.82, 90% interval 0.78 to 0.86. Synonymous variants: 582 observed, 580.94 expected, observed/expected ratio (o/e) 1, 90% interval 0.94 to 1.07.
Homologues: Orthologues: chimpanzee PDZD8 (99% identical), macaque PDZD8 (94% identical), dog PDZD8 (91% identical), rabbit PDZD8 (90% identical), guinea pig PDZD8 (88% identical), mouse Pdzd8 (87% identical), rat Pdzd8 (87% identical), zebrafish pdzd8 (56% identical), tropical clawed frog PDZD8 (55% identical), Caenorhabditis elegans pdzd-8 (24% identical), Drosophila melanogaster Pdzd8 (23% identical).
Diseases named in the same sentence as PDZD8 in open-access papers:
PDZD8 is named in the same sentence as 30 diseases in open-access papers, as found by Europe PMC text mining. Sharing a sentence is not in itself a finding about the gene and the disease. The quoted sentences say what the papers report.
gastric cancer (3 papers, 2022 to 2025). A primary or metastatic malignant neoplasm involving the stomach. "PDZD8 expression in gastric cancer was correlated with invasion of primary tumors (T factor) and pathological stage." (PMID 35409367, 2022). "SUN treatment resulted in a decrease in PDZD8 protein levels in both gastric cancer cell lines in whole-cell lysate and mitochondrial fraction." (PMID 35409367, 2022). "In support, knockdown of PDZD8 using siRNA has been shown to increase mitochondrial volume and oxidative stress, and to suppress mitochondrial respiration via mitochondrial Fe2+ accumulation, in human gastric cancer cell lines." (PMID 40016860, 2025). "Moreover, PDZD8, another Ca2+-regulating protein in MAMs, was found to exhibit increased expression levels in stomach cancer tissue compared with normal tissue and is involved in the proliferation and metastasis of stomach cancer." (PMID 38172597, 2024). "Therefore, we knocked down PDZD8 using siRNA and examined its role in the gastric cancer cell lines." (PMID 35409367, 2022). "Notably, sunitinib, a kinase inhibitor, attenuates the proliferation of stomach cancer cells, as demonstrated in the human gastric cancer cell lines TMK1 and MKN74, by decreasing the PDZD8 protein level." (PMID 38172597, 2024). "That is, in the present study, PDZD8 protein was expressed specifically in gastric cancer, but not in normal gastric tissue." (PMID 35409367, 2022). "PDZD8 may be a newly discovered off-target for SUN, and that the combined use of PTE with SUN significantly promotes antitumor activity in gastric cancer cell lines." (PMID 35409367, 2022). "Furthermore, the results from our study show that PDZD8 protein is specifically expressed in gastric cancer, and no increase in PDZD8 protein was observed in non-cancerous tissues such as adenomas or intestinal metaplasia." (PMID 35409367, 2022). "However, previous mRNA expression profiling data in gastric cancer have not shown that PDZD8 is highly expressed in gastric cancer." (PMID 35409367, 2022).
Intellectual disability (3 papers, 2022 to 2025). "Intellectual developmental disorder with autism and dysmorphic facies (IDDADF) is a rare syndromic intellectual disability (ID) caused by homozygous disruption of PDZD8 (PDZ domain-containing protein 8), an integral endoplasmic reticulum (ER) protein." (PMID 40016860, 2025). "Mutations of the PDZD8 gene in humans have been associated with intellectual disability (ID), providing further support for an important role of PDZD8 in the brain." (PMID 36658656, 2023). "Mutations of the PDZD8 gene in humans have been associated with intellectual disability (ID) due to neurodevelopmental disabilities, providing further evidence for an important role of PDZD8 in the brain." (PMID 36658656, 2023). "Mutations in human PDZD8 have also been reported to be associated with abnormal brain development and intellectual disability." (PMID 36465123, 2022).
posttraumatic stress disorder (3 papers, 2020 to 2022). "It is of note that PDZD8 mutation is a risk factor for posttraumatic stress disorder in humans, and further investigation into the function of the protrudin-PDZD8 complex might therefore shed light on the etiology of this disorder." (PMID 33172474, 2020).
dyslipidemia (2 papers, 2022 to 2023). "This study demonstrates for the first time that PDZD8 plays a role in promoting lipophagy and that deficiency of PDZD8 leads to dyslipidemia in the mammalian brain." (PMID 36465123, 2022). "We also show that PDZD8-KO mice with dyslipidemia in the brain exhibit restricted growth, hyperactivity, decreased anxiety and fear, increased sensorimotor gating, and reduced cued fear conditioned memory and working memory." (PMID 36658656, 2023). "PDZD8 may therefore be a key molecule in elucidating the relationship between dyslipidemia and inflammation-dependent neurological disorders in the brain." (PMID 36465123, 2022).
HIV-1 infection (2 papers, 2016 to 2021). The type species of lentivirus and the etiologic agent of acquired immunodeficiency syndrome (AIDS). "The cytoskeletal protein PDZD8 interacts with Gag involving those regions of the polyprotein associated with early post-entry events; knockdown of this cellular cofactor inhibits HIV-1 infection and negatively affects viral capsid stability, whereas PDZD8 overexpression enhances infection by HIV-1." (PMID 26797638, 2016). "PDZD8 is a poorly understood protein that has been shown to regulate microtubule stability through an interaction with moesin and microtubule stability at the viral synapse is likely to be important for HIV-1 infection." (PMID 26797638, 2016). "However, recent findings using cell lines in which PDZD8 expression has been eliminated by the CRISPR-CAS system indicated that HIV-1 infection is not affected by loss of this host protein." (PMID 26797638, 2016). "However, PDZD8-knockout cells were still able to be infected at the same level as PDZD8-expressing cells indicating that PDZD8 is not essential for HIV-1 infection, further demonstrating the adaptability of HIV-1." (PMID 33572761, 2021).
lung adenocarcinoma (2 papers, 2022 to 2025). A carcinoma that arises from the lung and is characterized by the presence of malignant glandular epithelial cells. "Expression of Concern: Wei W, Wang C, Wang L, Zhang J. circ_0020123 promotes cell proliferation and migration in lung adenocarcinoma via PDZD8." (PMID 40181840, 2025).
adenoma (1 paper, 2022). A neoplasm arising from the epithelium. "The expression level of PDZD8 was low in normal gastric mucosa, intestinal metaplasia, and adenoma, but was present at high levels in adenocarcinomas." (PMID 35409367, 2022). "The expression of PDZD8 was detected in adenocarcinomas but not in normal gastric mucosa, intestinal metaplasia, and adenomas." (PMID 35409367, 2022).
Anxiety (1 paper, 2023). Intense feelings of nervousness, tension, or panic often arise in response to interpersonal stresses. "PDZD8-KO mice showed reduced anxiety and fear, but also reduced working memory, so it is unclear which of them is responsible for the reduced cued fear conditioned memory." (PMID 36658656, 2023). "However, the percentage of entries into the open arms and percent time spent in the open arms were significantly higher for PDZD8-KO mice than for WT animals, suggestive of reduced anxiety- and fear-related behaviors in the mutant animals." (PMID 36658656, 2023). "However, time spent in the center area during the intervals from 20 to 25 min and from 30 to 35 min was greater for PDZD8-KO mice than for WT mice, suggestive of a reduced level of anxiety in the former animals." (PMID 36658656, 2023). "In addition, PDZD8-KO mice exhibit growth retardation, hyperactivity, reduced anxiety and fear, increased sensorimotor gating, and impaired cued fear conditioned memory and working memory." (PMID 36658656, 2023). "We also show that PDZD8-KO mice with abnormal accumulation of CEs in the brain exhibit abnormalities in emotion, cognition and adaptive behavior including restricted growth, hyperactivity, and decreased anxiety and fear, similar to Pdzd8tm1b mice." (PMID 36658656, 2023). "In contrast, PDZD8-KO mice (exon 1-deleted) showed novel phenotypes such as increased sensorimotor gating and reduced cued fear conditioned memory and working memory, as well as the similar abnormalities to Pdzd8tm1b mice such as restricted growth, hyperactivity, and decreased anxiety and fear." (PMID 36658656, 2023). "While anxiety and fear are increased in PTSD, however, they are decreased in PDZD8-KO mice, which discrepancy cannot be explained at this time." (PMID 36658656, 2023).
autism (1 paper, 2025). Persistent deficits in social interaction and communication and interaction as well as a markedly restricted repertoire of activity and interest as well as repetitive patterns of behavior. "The discovery of a third family with IDDADF caused by biallelic disruption of PDZD8 permitted identification of a core clinical phenotype consisting of developmental delay, ID, autism, and facial dysmorphism." (PMID 40016860, 2025). "In summation, this study identifies a third family with IDDADF caused by biallelic disruption of PDZD8, thereby permitting the identification of a core clinical phenotype including autism." (PMID 40016860, 2025). "However, cross-species support is provided by PDZD8-deficient Pdzd8tm1b mice that exhibit phenotypes comparable to ID and autism." (PMID 40016860, 2025). "The identification of six IDDADF cases (4 male and 2 female), with three different PDZD8 PTC variants and ethnic origins, permits the identification of a core clinical phenotype affecting all cases, consisting of developmental delay, ID, autism, and facial dysmorphism." (PMID 40016860, 2025). "Intellectual developmental disorder with autism and dysmorphic facies (IDDADF; OMIM #620021) is a very rare syndromic ID caused by homozygous premature termination codons (PTCs) in PDZD8, encoding PDZ domain-containing protein 8 (PDZD8)." (PMID 40016860, 2025). "The manifestation of autism in all six known IDDADF cases, with ASD diagnosed in five cases (83%) including both females, suggests that this trait may be fully penetrant in PDZD8 PTC variant homozygotes regardless of sex." (PMID 40016860, 2025).
Cognitive impairment (1 paper, 2022). Abnormal cognition is characterized by deficits in thinking, reasoning, or remembering. "In common with other neurodevelopmental disorders, the cognitive impairment associated with PDZD8 disruption is therefore likely to represent a synaptopathy resulting from synaptic dysfunction." (PMID 35227461, 2022). "Our finding that interference of PDZD8 orthologs resulted in long-term memory deficits in mice and fruit flies provides cross-species substantive evidence linking PDZD8 disruption and cognitive impairment." (PMID 35227461, 2022).
Gaucher disease (1 paper, 2024). Gaucher disease (GD) is a lysosomal storage disorder encompassing three main forms (types 1, 2 and 3), a fetal form and a variant with cardiac involvement (Gaucher disease - ophthalmoplegia - cardiovascular calcification or Gaucher-like disease). "However, our lipidome analysis indicated that Pdzd8 deletion did not induce cardiolipin accumulation, but rather led to the accumulation of glucosylceramide in podocytes, which is similar to that in Gaucher disease." (PMID 39115943, 2024).
heart failure (1 paper, 2025). Inability of the heart to pump blood at an adequate rate to meet tissue metabolic requirements. "MR analysis identified significant causal associations between the genes implicated in BW loss (ADD3, HSPA12A, SLC18A2, PDZD8, DUSP5, CASP7) as well as EF% and LV volumes (GPC6, UGGT2, SLAIN1, POU4F1, MBNL2) in BXD mice post-DOX and heart failure (HF) outcomes in humans." (PMID 40321772, 2025).
Hypoglycemia (1 paper, 2025). A decreased concentration of glucose in the blood. "Since functional PDZD8 is required for glutaminolysis in response to hypoglycemia, it is plausible that the PDZD8 deficiency and locomotor hyperactivity of Pdzd8tm1b mice require them to obtain proportionately more fuel from the diet in order to meet their energy demands." (PMID 40016860, 2025).
Obesity (1 paper, 2024). Accumulation of substantial excess body fat. "Additionally, electron microscopy revealed the accumulation of abnormal, fatty endosomes in Pdzd8-deficient podocytes during obesity-related kidney diseases." (PMID 39115943, 2024). "To elucidate the impact of Pdzd8 deletion–induced mitochondrial and endosomal abnormalities on podocyte injury, we established an accelerated obesity–related kidney disease model." (PMID 39115943, 2024). "Our findings demonstrated that Pdzd8 deletion exacerbated podocyte injury in an accelerated obesity–related kidney disease model." (PMID 39115943, 2024). "Pdzd8 deletion exacerbates podocyte injury in an accelerated obesity–related kidney disease model." (PMID 39115943, 2024). "Pdzd8 deletion induces podocyte endosomal malformation in an obesity-related kidney disease." (PMID 39115943, 2024).
Sepsis (1 paper, 2023). Sepsis is defined as life-threatening organ dysfunction caused by a dysregulated host response to infection. "However, sepsis cases with increased levels of mRNA of DHCR7, GABARAPL2, MAOA, MPO, PDZD8, and TFRC had worse overall survival." (PMID 38011291, 2023).
virus infection (1 paper, 2020). "PDZD8 has also been associated with virus infection, such as that by human immunodeficiency virus or herpes simplex virus, with this association possibly being related to PDZD8 function in endosome sorting of viral particles in human cells." (PMID 32917905, 2020).
cancer (5 papers, 2022 to 2025). A tumor composed of atypical neoplastic, often pleomorphic cells that invade other tissues. "Both SUN treatment and PDZD8 knockdown reduced oxidative phosphorylation, and both basal respiration and ATP production were reduced to approximately 70% of the control in both cancer cell lines." (PMID 35409367, 2022). "This indicates that MAM formation by PDZD8 might be characteristic of undifferentiated and proliferative tissues such as cancer." (PMID 35409367, 2022). "PDZD8 is considered to be a MAM protein, but its role in cancer cells has not been clarified thus far." (PMID 35409367, 2022).
tumor (3 papers, 2022 to 2025). "Xenograft tumor model in nude mice will be established in future studies to explore the influence of circ_0020123/miR-1283/PDZD8 on tumor growth and metastasis in vivo." (PMID 35415250, 2022).
infection (2 papers, 2016 to 2021). The state of being infected such as from the introduction of a foreign agent such as serum, vaccine, antigenic substance or organism. "While the underlying reason for this apparent discrepancy remain unclear, it is possible that long-term knockout of PDZD8 requires the evolution of compensatory processes for cell survival and which negate the effect of PDZD8 loss on infection." (PMID 34229718, 2021). "Follow up studies further identified a novel moesin interacting factor PDZ domain-containing protein 8 (PDZD8) which not only induced MT stabilization and promoted early infection at the initiation of reverse transcription, but also bound to HIV-1 CA and affected the stability of incoming core." (PMID 34229718, 2021).
PDZD8 also shares sentences with these, for which no sentence is quoted: neurological disorders (2 papers); adenocarcinoma (1); Alzheimer disease (1); Charcot-Marie-Tooth disease (1); developmental delay (1); Insulin resistance (1); kidney disease (1); neurodegenerative disease (1); neurodevelopmental disabilities (1); neurodevelopmental disorder (1); stomach cancer (1).